ENSG00000271741 (novel transcript, ZMYM6-ZMYM6NB readthrough)
Gene: Protein-coding gene on chromosome 1 (34,981,533 to 35,031,741, reverse strand). Ensembl gene ENSG00000271741.
Genetic constraint (gnomAD): Missense variants: 748 observed, 869.26 expected, observed/expected ratio (o/e) 0.86, 90% interval 0.81 to 0.91. Synonymous variants: 281 observed, 299.75 expected, observed/expected ratio (o/e) 0.94, 90% interval 0.85 to 1.03.